TNF (tumor necrosis factor)
Diseases named in the same sentence as TNF in open-access papers (continued):
Sharing a sentence is not in itself a finding about the gene and the disease.
endothelial dysfunction (continued). "While in prediabetes endothelial dysfunction is a precursor to more severe vascular issues, in MetS the inflammation and the oxidative stress are more pronounced, particularly involving tumor necrosis factor-α (TNF-α)." (PMID 40556956, 2025). "Other studies suggest that pro-inflammatory mediators, such as TNF-α, IL-6, and IL-8, enter the circulation and create a systemic inflammatory environment, which may lead to endothelial dysfunction and exacerbate pain." (PMID 40771919, 2025). "This study demonstrates significant endothelial dysfunction and elevated levels of inflammatory cytokines, particularly IL-6 and TNF-α, in patients with acute coronary syndrome (ACS) compared to those with stable coronary artery disease (CAD) or chest pain of non-epicardial CAD ischemic origin." (PMID 40310443, 2025). "Chronic activation of the immune system results in the production of proinflammatory cytokines, such as interleukin-6 (IL-6), tumor necrosis factor-alpha (TNF-α), and C-reactive protein (CRP), which are central to the inflammatory cascade associated with endothelial dysfunction and vascular damage." (PMID 40787484, 2025). "In conclusion, CUD003, a novel synthetic Cur derivative, ameliorates LPS-induced endothelial dysfunction primarily by inhibiting inflammation and oxidative stress, as demonstrated by reduced TNF-α and COX-2 expression, along with decreased O2− production and lipid peroxidation." (PMID 41009419, 2025). "According to Liu’s study, diminished HIF-1α expression during the placental ischemic process leads to excessive apoptosis, the reduced expression of VEGF and PlGF, and the overexpression of sFlt1, sEng, and TNF-α, leading to endothelial dysfunction and elevated systolic blood pressure." (PMID 41515555, 2025). "These include the endogenous inhibitor of nitric oxide (NO) synthase, asymmetric dimethyl-arginine (ADMA), considered as a marker of endothelial dysfunction and CVD risk, and inflammatory cytokines such as tumor necrosis factor-α (TNF-α), which is associated with vascular pathophysiology." (PMID 40643525, 2025). "Additionally, inflammation, marked by elevated cytokines like tumor necrosis factor-alpha (TNF-α) and interleukin-6 (IL-6), contributes to myocardial injury and endothelial dysfunction." (PMID 40313442, 2025). "Thus, ROS directly influence psoriatic cytokine milieu including TNFα, IL- 22, and IL- 23/Th17 axis molecules and concomitant neutrophils- and monocytes-derived myeloperoxidase promotes endothelial dysfunction and inflammation." (PMID 40358870, 2025). "Consistent with these hematologic abnormalities, hyperglycemic patients showed significantly higher levels of ESR, CRP, ferritin, and fibrinogen, suggesting a pronounced proinflammatory milieu driven by oxidative stress, endothelial dysfunction, and activation of the IL-6/TNF-α cytokine axis." (PMID 41156159, 2025). "Elevated cytokines such as IL-6 and TNF-α exacerbate systemic inflammation, promoting endothelial dysfunction and microvascular remodeling.Furthermore, antiphospholipid antibodies contribute to thrombotic microangiopathy, resulting in vascular occlusion and ischemia." (PMID 40589745, 2025). "Tumour necrosis factor-alpha (TNF-α) and interleukin-1 beta (IL-1β) have been shown to play integral parts in systemic inflammation and endothelial dysfunction, while interleukin-6 (IL-6) and interleukin-8 (IL-8) have been demonstrated to contribute to vascular resistance and thrombosis." (PMID 41439053, 2025). "Hyperinsulinemia and dyslipidemia can activate innate immune cells, leading to the release of pro-inflammatory cytokines such as IL-1β, IL-6, and TNF-α, which in turn promote endothelial dysfunction, vascular stiffness, and sodium retention—key hallmarks of hypertension." (PMID 40944247, 2025). "One potential mechanism by which hsa-miR-27b-3p may mitigate TNF-α-induced endothelial dysfunction and mitochondrial dysfunction is through the activation of the forkhead box O pathway." (PMID 41462406, 2025).
endothelial dysfunction (continued). "The inflammatory component involves cytokine cascades—particularly Interleukin 1 beta (IL-1β) and Tumor Necrosis Factor alpha (TNF-α)—which exacerbate endothelial dysfunction through the NF-κB-mediated upregulation of adhesion molecules and matrix metalloproteinases." (PMID 40507729, 2025). "Furthermore, inflammation contributes to preeclampsia progression, as elevated levels of tumor necrosis factor-alpha (TNF-α) and interleukin-6 (IL-6) promote immune dysregulation, exacerbate vascular inflammation, and increase endothelial dysfunction." (PMID 40218901, 2025). "Additionally, inflammatory mediators, including TNF-α and IL-6, are upregulated, contributing to endothelial dysfunction and hepatocellular apoptosis." (PMID 40005408, 2025). "Elevated levels of pro-inflammatory cytokines, such as tumour necrosis factor-alpha (TNF-alpha), interleukin-1 (IL-1), and interleukin-6 (IL-6), contribute to endothelial dysfunction by reducing the bioavailability of nitric oxide, increasing oxidative stress, and impairing vasodilation." (PMID 40958238, 2025). "While our study establishes SLC3A2 downregulation and ferroptosis activation as pivotal in high glucose/TNFα-induced endothelial dysfunction, bioinformatics analysis revealed concurrent enrichment of JAK-STAT and TGF-β signaling in dysfunctional cells, suggesting multipathway cross-talk." (PMID 40703306, 2025). "In addition to ROS, inflammatory cytokines such as interleukin-1β (IL-1β) and tumor necrosis factor-alpha (TNF-α) contribute to endothelial dysfunction by promoting leukocyte adhesion and increasing vascular permeability." (PMID 40863347, 2025). "Furthermore, inflammatory cytokines such as interleukin-6 (IL-6) and tumor necrosis factor-alpha (TNF-α) enhance endothelial dysfunction and trigger the coagulation cascade, which further adds to the hypercoagulable condition." (PMID 41377299, 2025). "Key findings include the persistent activation of innate and adaptive immune responses, elevated levels of proinflammatory cytokines [e.g., interleukin-1 beta (IL-1β), IL-6, and tumor necrosis factor alpha (TNF-α)], and evidence of endothelial dysfunction and microclot formation​​." (PMID 40821254, 2025). "In SLE patients, particularly those with high disease activity, significant endothelial dysfunction may occur, which is likely linked to elevated SLEDAI scores and increased levels of proinflammatory cytokines such as TNF-α, IL-1, IL-6, and interferon (IFN)-α." (PMID 41204247, 2025). "Dicarbonyl compounds such MGO, GO, and 3-DG are critical precursors in AGE formation and known contributors to diabetic complications, including inflammation via increased expression of pro-inflammatory cytokines such as TNF-α and IL-1, endothelial dysfunction, nephropathy, and neuropathy." (PMID 40944124, 2025). "It results in macrophage activation, release of pro-inflammatory cytokines (IL-1β, TNF-α), nitric oxide overproduction, and subsequent hypotension and endothelial dysfunction—phenomena previously observed in early clinical trials of cell-free Hb as an oxygen therapeutic." (PMID 41373848, 2025). "Furthermore, lonely individuals often experience higher levels of pro-inflammatory cytokines, including interleukin-6 (IL-6) and tumor necrosis factor-alpha (TNF-α), which contribute to endothelial dysfunction and increased thrombogenic potential." (PMID 40291206, 2025). "On the other hand, one can speculate that immunosuppressants may indirectly exercise a protective role against endothelial dysfunction by inhibiting tumor necrosis factor-alpha (TNF-α)." (PMID 38673546, 2024). "Additionally, TNF, a pro-inflammatory cytokine produced by activated leukocytes, targets endothelial cells and triggers a cascade of events, leading to endothelial dysfunction and accelerated development of AS." (PMID 39072329, 2024).
endothelial dysfunction (continued). "Multi animal studies has proposed that the direct myocardial effects of various pro-inflammatory cytokines (IL-1, IL-2, IL-6, tumor necrosis factor-α, TNF-α) has resulted in obvious impairment of contractility, LV dilatation and induction of endothelial dysfunction." (PMID 38321374, 2024). "Preincubation with AMI prevented TNF-α-induced endothelial dysfunction." (PMID 36103099, 2024). "However, TNF-α overproduction and secretion due to increased body fat contribute to vascular inflammation and endothelial dysfunction." (PMID 39742290, 2024). "The changes in blood flow and endothelial dysfunction in the liver microcirculation may be partially explained by increased levels of inflammatory mediators such as TNF-α, IL-1β, and chemokines." (PMID 39337863, 2024). "Additionally, an imbalance in cytokine production, with elevated levels of pro-inflammatory cytokines such as TNF-α and IL-6 and reduced levels of anti-inflammatory cytokines, contributes to endothelial dysfunction and impaired placentation." (PMID 39062815, 2024). "Elevated TNF-α levels in renal or plasma tissues, in conjunction with concurrent oxidative stress development and elevated reactive oxygen species, may exacerbate endothelial dysfunction." (PMID 39171117, 2024). "Endothelial dysfunction may contribute to the accumulation of leukocytes and the induction of tissue damage, as well as the further release of cytokines (IL-6, IL-1B, and TNF-alpha)." (PMID 39598310, 2024). "Finally, overexpression of pro-inflammatory cytokines (IL-18, IL-33, and TNF-α) has been identified in RA patients with vascular impairment, confirming the key role in both the inflammatory process and the development of endothelial dysfunction." (PMID 39234606, 2024). "Progression of endothelial dysfunction is associated with the increase in the expressions of chemokines, cellular adhesion molecules, and cytokines, such as VCAM-1, and systemic inflammatory markers, such as TNF-α, among others." (PMID 38195507, 2024). "Moreover, this study investigated the contribution of only some cytokines (TNF-α, IL-6) in the development of endothelial dysfunction, but a much higher number of cytokines are increased in pSS." (PMID 37762225, 2023). "The biomarkers associated with an increased risk of cardiovascular events include fibrinogen and endothelial dysfunction, as well as the cytokines IFN-γ and TNF-α, and these two inflammatory markers have also been shown to be predictive of future cardiovascular events." (PMID 37568441, 2023). "Tumor necrosis factor (TNF-α) was used to induce endothelial dysfunction." (PMID 37893034, 2023). "Damage to endothelial cells leads to endothelial dysfunction, mediated by several inflammatory biomarkers such as TNF-α (tumor necrosis factor-α), reactive oxygen species, autoantibodies, and oxidized low-density lipoproteins (LDLs), ultimately leading to the formation of atherosclerotic plaques." (PMID 37859889, 2023). "Moreover, the simultaneous inhibition of IL-1β and TNF-α signaling pathways prevented smoking-induced endothelial dysfunction." (PMID 37240069, 2023). "Also, VAT, epicardial fat, and vascular tissue secrete proinflammatory cytokines (eg, TNF‐α [tumor necrosis factor‐α], IL‐1 [interleukin‐1], and IL‐6 [interleukin‐6]), which contribute to microvascular endothelial dysfunction and reduced vascular compliance." (PMID 37345755, 2023). "Additionally, adiponectin, which plays a protective role against endothelial dysfunction and arteriosclerosis, was decreased, and inflammatory adipokines, such as leptin and TNF-α, were increased in the HFHSD-only groups." (PMID 37047458, 2023). "The PVAT in lupus mice exhibited increased infiltration of immune cells and expression of pro-inflammatory cytokines (e.g., IL-1β, IL-6, TNFα, IFNγ), along with decreased expression of adiponectin, which likely promotes endothelial dysfunction and vascular wall remodeling." (PMID 37006244, 2023).
endothelial dysfunction (continued). "TNF-α and IL-6 are involved in the appearance of endothelial dysfunction." (PMID 37762225, 2023). "Racial differences in EC responses to stimuli, particularly TNF, could play an important role in the promotion of endothelial dysfunction, plaque development, and consequent CVD." (PMID 37834170, 2023). "Specifically, the interaction between TNF-α and endothelial dysfunction may be crucial in this process." (PMID 37445555, 2023). "In addition to lipid metabolism, ANGPTL7 also plays a role in oxidative stress, inflammation and cell adhesion through its role in TNF-α-induced endothelial dysfunction." (PMID 36017324, 2022). "Previous studies suggested that hyperlipidemia, especially hypercholesterolemia, leads to the augmentation of oxidative and nitrosative stress and enhanced proinflammatory cytokine production (e.g., TNF-α and IL-6), consequently contributing to cardiac and endothelial dysfunction." (PMID 35806390, 2022). "Eventually, serum tumor necrosis factor-α (TNF-α), interleukin-6 (IL-6), and C-reactive protein (CRP), which respond to inflammatory levels, were eventually elevated, indicating a link between the inflammatory response caused by IR and endothelial dysfunction." (PMID 36589857, 2022). "Other inflammatory cells involved in this cascade promote the production of cytokines such as TNF-α, which may promote endothelial dysfunction and enhanced LDL particle transcytosis into the arterial intima, also enhancing LDL particle retention." (PMID 36558530, 2022). "Further, silibinin may reduce pro-inflammatory effects and endothelial dysfunction by regulating expression patterns of TNF-α, IL-6 and ET-1 in blood plasma." (PMID 35821883, 2022). "One of the mechanisms for TNFα-induced endothelial dysfunction could be the vascular barrier dysfunction and the increased vascular permeability." (PMID 35954226, 2022). "Interleukine-1β (IL-1β), interleukine-6 (IL-6), tumor necrosis factor-α (TNF-α) and CRP could represent new therapeutic targets for anti-inflammatory treatment in endothelial dysfunction for reducing the risk of atherosclerotic cardiovascular disease (ASCVD)." (PMID 35204113, 2022). "Mild systemic inflammation, characterized by a slightly increased level of TNF-α, and endothelial dysfunction, marked by elevated ET-1, could be liaisons between aging, COPD, and CVD comorbidities." (PMID 35984178, 2022). "Importantly, we specifically investigated TNF-α, Il-6, and sFlt-1 because they are key players in PE pathogenesis and severe endothelial dysfunction." (PMID 35163594, 2022). "TNF-α especially, but also IL-6, seem to contribute to endothelial dysfunction." (PMID 35628831, 2022). "Overexpression of miR-21 promotes endothelial dysfunction in HUVECs treated with TNF-α." (PMID 36561848, 2022). "Moreover, infliximab reversed TNF-α induced endothelial dysfunction as well as the increase in oxLDL, LOX-1, and Arg2." (PMID 36555579, 2022). "Furthermore, treatment of cells with 60 °C OPWE reversed TNF-α-induced endothelial dysfunction in vitro primarily through anti-inflammatory action, suggesting the potential to upcycle OPW as a natural product to promote vascular health." (PMID 36139842, 2022). "It is speculated that during acute SARS-CoV-2 infection, the overwhelming inflammation mediated by TNF-α leads to the systematic injury of endothelial cells, and subsequent endothelial dysfunction remains even after the inflammation subsides." (PMID 35237624, 2022). "In addition, inflammatory cytokines such as TNFα are considered as important mediators in endothelial dysfunction in systemic diseases or pathological conditions where inflammation is involved." (PMID 35954226, 2022). "This chronic inflammation through increased tumor necrosis factor alpha (TNF) levels, and increased reactive oxygen species (ROS) causing endothelial dysfunction with reduced nitic oxide (NO) levels leads to proliferation and phenotypic switch of vascular smooth muscle cells (VSMCs)." (PMID 35585282, 2022).
endothelial dysfunction (continued). "Moreover, the pro-inflammatory cytokines serum tumor necrosis factor-α(TNF-α) and Interleukin-6 (IL-6) have been found increased in the circulation of women with GDM, which are associated with endothelial dysfunction, and also increased in women with PE." (PMID 35252402, 2022). "In OSA patients, repeated oxygen desaturations and subsequent endothelial dysfunction induce the release of strong proinflammatory biomarkers, particularly tumor necrosis factor alpha (TNF-α), interleukin-6 (IL-6), C-reactive protein (CRP), leptin, and reactive oxygen species (ROS)." (PMID 34349888, 2021). "However, this is less clear in the case of endothelial dysfunction, where following TNFα stimulation of HUVECs, carvedilol increased PTGS2 expression while bisoprolol decreased it." (PMID 34362171, 2021). "The pharmacological effects of TNFα/IL1β neutralizing antibodies as well as FAK inhibitor on CAR-T therapy-induced endothelial dysfunction still need to be verified in vivo, and the optimization of the interfering strategies might also be needed." (PMID 34093519, 2021). "In endothelial dysfunction, activation of the nuclear factor-kappa B (NF-κB) pathway has highlighted elevated levels of pro-inflammatory cytokines such as tumor necrosis factor-alpha, interleukin-1beta (IL-1 β), interleukin-6 (IL-6), and interferon gamma (IFN-γ)." (PMID 33467601, 2021). "TNF-α is related to the pathogenesis of endothelial dysfunction." (PMID 34681733, 2021). "This is compatible with the increased levels of TNFα and IL-6 measured in our study and may lead to endothelial dysfunction." (PMID 34460845, 2021). "DHM improved TNF-α-induced endothelial dysfunction by inhibiting miR-21." (PMID 35115939, 2021). "A secondary aim was to examine whether the inflammatory state and tumor necrosis factor α (TNFα)-induced endothelial leukocyte adhesion, a key feature of endothelial dysfunction, was improved after this time." (PMID 33959024, 2021). "Taken together, the increased levels of IL-1α, IL-6, and TNF-α in MSK1/2 KO mice could explain the observed endothelial-dysfunction in this study, although the mechanisms of diminished NO bioavailability may be multi-modal and requires further scrutiny." (PMID 34445361, 2021). "TNF-α plays an important role in endothelial dysfunction and inflammation." (PMID 33917744, 2021). "Indeed, TNF-α has been characterized as a critical molecule in uremia-induced vascular disease and that it can promote both, vascular calcification and endothelial dysfunction." (PMID 34858433, 2021). "TNFα was used to induce endothelial dysfunction in primary cultured HUVECs." (PMID 34362171, 2021). "The pro-inflammatory cytokine storm, with elevated levels of interleukin-6 (IL-6), IL-2 receptor, and tumor necrosis factor-α, could also participate in endothelial dysfunction and leukocyte recruitment in the microvasculature." (PMID 32546188, 2020). "Other crucial proinflammatory cytokines such as TNF-α and IL-1β may stimulate leukocyte adherence and migration, which may worsen endothelial dysfunction." (PMID 32410856, 2020). "Our data suggest a central role for TNF in endothelial dysfunction and vascular disease." (PMID 32976527, 2020). "This experimental model demonstrated endothelial dysfunction, manifested by the inflammatory cytokine TNF-α as well as by adhesion molecules that are indicators of endothelial damage, such as ICAM-1 (87.6%, 122 ± 9 vs 65 ± 5, p < 0.0001) and VCAM-1 (29.4% 110 ± 10 vs 85 ± 2, p < 0.05)." (PMID 32795274, 2020). "Other authors have shown attenuating in vitro effects of urolithin A on endothelial dysfunctions induced by oxidized LDL through the beneficial modulation of TNF-α, IL-6, endothelin 1, PPAR-γ, ICAM-1 (intercellular adhesion molecule 1), and MCP-1 (monocyte chemotactic protein 1) expression." (PMID 33322602, 2020).